SQLE (squalene epoxidase)
Diseases named in the same sentence as SQLE in open-access papers (continued):
Sharing a sentence is not in itself a finding about the gene and the disease.
cardiovascular disease (2 papers, 2011 to 2018).
SQLE also shares sentences with these, for which no sentence is quoted: atherosclerosis (4 papers); lung carcinoma (3); Hypercholesterolemia (2); melanoma (2); non-alcoholic steatohepatitis (2); pancreatic adenocarcinoma (2); acute myeloid leukemia (1); Alzheimer disease (1); bladder cancer (1); Breast tumor (1); dyslipidemia (1); genetic disorder (1); glioblastoma (1); Granuloma (1); hematological disease (1); Huntington disease (1); lathosterolosis (1); Listeria infection (1); metabolic disorders (1); nasopharyngeal carcinoma (1); Pleural effusion (1); renal carcinoma (1); Rett syndrome (1); rhabdomyosarcoma (1); sarcoidosis (1); small cell lung carcinoma (1); soft tissue tumor (1).